AR (androgen receptor)
Diseases named in the same sentence as AR in open-access papers (continued):
Sharing a sentence is not in itself a finding about the gene and the disease.
prostate carcinoma (continued). "Androgen deprivation therapy (ADT) is the mainstay treatment for metastatic prostate cancer because of both benign prostate tissue and malignant prostate tissue express androgen receptor (AR), which prostate cancer cells require for their growth and cancer progression." (PMID 39517121, 2024). "Therefore, innovative targets beyond the androgen-AR axis are required to achieve substantial progress against prostate cancer." (PMID 39146021, 2024). "Studies have elucidated the relation between AR and Wnt signaling pathway in prostate cancer." (PMID 38372868, 2024). "Furthermore, a recent report has revealed that acetylated H2A.Z can generate new ectopic enhancers, resulting in aberrant gene transcriptional activation in androgen receptor (AR) dependent prostate cancer." (PMID 38542118, 2024). "The use of androgen receptor pathway inhibitors (ARPIs) has led to an increase in the proportion of AR-null prostate cancer, including neuroendocrine prostate cancer (NEPC) and double-negative prostate cancer (DNPC), but the mechanism underlying this lineage transition has not been elucidated." (PMID 38254880, 2024). "However, additional studies are required to understand the molecular pathways through which inflammasome-mediated inflammatory response is involved under normal, hypoxia, androgen receptor-mediated progression and metastasis of prostate cancer." (PMID 39769450, 2024). "Similarly, 27HC promotes the proliferation of prostate cancer cells and induces resistance to docetaxel via an androgen receptor (AR)-dependent mechanism." (PMID 38617549, 2024). "The p300/CBP reader bromodomain inhibitor CCS1477 is currently in early-phase clinical trials; given this, we tested CCS1477 and another reader bromodomain inhibitor, GNE-049, for their ability to attenuate p300/CBP activity in AR-positive prostate cancer cells." (PMID 38586029, 2024). "Previous studies have leveraged integrative genomic analyses to elucidate the genomic and epigenomic drivers of mCRPC, such as the occurrence of mutations in the AR region, genes associated with RB1 biallelic inactivation, and the presence of hypomethylated regions in prostate cancer-specific genes." (PMID 38396008, 2024). "Altogether, our findings suggest that p300/CBP complexes retain their acetyltransferase activity for the H2BNT lysine residues despite the attenuation of the reader bromodomain, which sustains AR enhancer activity and triggers a distinct oncogenic gene program in prostate cancer cells." (PMID 38586029, 2024). "In vitro, EIQPN inhibit the androgen-independent proliferation of various AR-positive prostate cancer cells, and block the tumor growth of androgen-independent prostate cancer cells in xenograft mouse models, indicating EIQPN serves as a potential therapeutic agent for CRPC." (PMID 39359255, 2024). "Additionally, ING1 and ING2, through their recruitment by the AR, have been shown to orchestrate the downregulation of the human telomerase reverse transcriptase subunit (hTERT) in prostate cancer cells." (PMID 38813086, 2024). "Prostate cancer positive for androgen receptor variant 7 (AR-V7) exhibits primary resistance to androgens because of the lack of the ligand-binding domain of the androgen receptor." (PMID 38627681, 2024). "A previous study reported that FoxA1 could modulated by SUMOylation during functional interplay with androgen receptor in prostate cancer cells." (PMID 39277582, 2024). "The key gene sets associated with prostate cancer across various omics profiles were obtained from the TCGA and SRA databases, including data from AR ChIP-seq, transcriptomic, single-cell transcriptomic, lncRNA, SNV, CNV, DNA methylation, and clinical data for prostate cancer patients." (PMID 38778150, 2024). "Importantly, this article also focuses on the correlation between circadian rhythms and androgen receptor signaling pathways, as well as the applicability of time therapy in prostate cancer." (PMID 39011396, 2024).
prostate carcinoma (continued). "The androgen receptor (AR) plays a vital role in prostate cancer growth and progression." (PMID 38791417, 2024). "Moreover, in primary prostate cancers with high AR expression, there was a tendency that the survival of the group with a high expression of FIiI was better than that with low FIiI expression." (PMID 39000020, 2024). "This novel mechanism of blocking AR biogenesis via E2F8 may provide an opportunity to control therapy‐resistant prostate cancer over the currently used AR antagonists designed to target different parts of the AR gene." (PMID 38605607, 2024). "As a result, combination therapy regimens incorporating copper ionophores alongside AR‐targeting drugs may offer increased flexibility and potentially broader efficacy in combating prostate cancer." (PMID 38859590, 2024). "Consequently, conventional endocrine therapies targeting androgen synthesis and/or androgen binding are prone to failure once these AR-Vs are overexpressed in prostate cancer." (PMID 38500100, 2024). "This was not unexpected, as all six patients with prostate cancer had disease progression on prior abiraterone treatment, and AR amplifications and point mutations in LBD are both associated with anti-androgen therapy resistance." (PMID 38086998, 2024). "The current research shows that FGFR signaling may help AR-null prostate cancer bypass AR signaling." (PMID 38254880, 2024). "Previous studies searching for inhibitors in the atypical NFκB signaling pathways identified a specific inhibitor of androgen receptor and p52 interaction resulting in reduced levels of cyclin D1 expression used for the treatment of castration-resistant prostate cancer." (PMID 38238702, 2024). "Despite gains from early diagnoses, androgen deprivation therapy (ADT) and androgen receptor (AR) signaling inhibitors (ARSIs), prostate cancer (PC) remains a major killer of men and the low survival of patients with distant metastases remains a major clinical challenge." (PMID 38866755, 2024). "Moreover, these compounds were biologically tested for their cytotoxic effects against androgen-sensitive (AR+LNCaP) and androgen-insensitive (AR-PC-3) human prostate cancer cell lines, in addition to normal human lung fibroblast (Wi38) as control." (PMID 39062524, 2024). "Third, beyond affecting the levels and phosphorylation of transcriptional regulators with central roles in prostate cancer growth and progression – AR, MYC, and BRD4 – CDKI-73 would blunt the oncogenic transcriptional programs activated by these factors via reducing pSer2-RNAPII." (PMID 39117800, 2024). "As such, the overexpression of AR leads to an increase in prostate cancer cell division." (PMID 38607014, 2024). "Recent studies have highlighted the inhibitory crosstalk between AhR and AR in prostate cancer." (PMID 39184676, 2024). "Spurred by the identification of androgen receptors (AR) as potential treatment targets in prostate cancer, clinicians and researchers have proposed the use of AR expression (as assessed by immunohistochemistry) as a criterion to stratify TNBC patients for AR-targeted therapies." (PMID 39335162, 2024). "Notably, androgen receptor signaling plays a role in regulating DNA repair genes, and inhibiting this pathway downregulates DNA damage repair in prostate cancer." (PMID 39526247, 2024). "Thus, the authors conclude that suppression of prostate cancer cells occurred by regulation of AR transcription and promotion of AR protein degradation." (PMID 38398553, 2024). "Interestingly, enzalutamide induced cancer cell migration in DU145 cells, which are AR-null prostate cancer cells." (PMID 38254786, 2024). "Similarly, AZGP1, as with other kinds of secreted proteins, was also verified to be involved in the process of the proliferation and metastasis of prostate cancer cells induced by the AR." (PMID 39771106, 2024).
prostate carcinoma (continued). "Notably, CLNS1A cooperates with the protein arginine methyltransferase 5, which functions as an epigenetic activator of androgen receptor transcription in castration-resistant prostate cancer." (PMID 39857609, 2024). "AR was suspected in promoting invasiveness of both androgen-dependent and independent prostate cancer; its expression affects EGFR-mediated signaling, and targeting EGFR in androgen-independent prostate cancer could inhibit tumor proliferation and invasion." (PMID 39459070, 2024). "Moreover, MST4 was shown to correlate with androgen receptor status in prostate cancer cell lines revealing male-specific functionality." (PMID 38233393, 2024). "We also validated the role of ES in the androgen receptor-positive prostate cancer cell line-LNCaP." (PMID 38671021, 2024). "Earlier research demonstrated that when AR-positive prostate cancer cells were treated with a proteolysis-targeting chimera (PROTAC) that degraded the ATPase subunits of the SWI/SNF chromatin remodeling complex (namely SMARCA2 and SMARCA4), it led to physical compaction of enhancer elements." (PMID 38586029, 2024). "The combination of the next-generation androgen receptor pathway inhibitor (enzalutamide) with palliative penectomy may extend survival for patients with penile metastasis from prostate cancer." (PMID 39868372, 2024). "Previous studies also indicated that stabilizing androgen receptor in mitosis could inhibits prostate cancer progression, indicating that we should choose suitable conditions to interfere ARG signaling (Vander Griend, Litvinov & Isaacs, 2007)." (PMID 38562999, 2024). "Importantly, loss of AR resulted in an enhanced expression of PAX6, which reprogramed the lineage plasticity of prostate cancer cells to develop NE phenotypes through the MET/STAT5A signaling pathway." (PMID 38745318, 2024). "We found that ID2 expression was increased in AR-null prostate cancer." (PMID 38254880, 2024). "This suggests an autophagy-inhibitory role of AR, which might promote prostate cancer progression by preventing excessive, cell death-promoting autophagy during nutrient limitation in the tumour microenvironment." (PMID 38910881, 2024). "In prostate cancer, androgen-activated nuclear AR functions as a classical transcription factor with relatively well-characterized transcriptional repertoire, including genes such as PSA, KLK2, FKBP5, and TMPRSS2, the alteration of which promotes prostate tumor aggressiveness." (PMID 38326303, 2024). "However, there is a need for additional studies on the mechanism of how EMT in prostate cancer is controlled by the interplay of AR with EMT-related transcription factor expression." (PMID 38384328, 2024). "Therefore, given the experience in prostate cancer, an interest in AR targeted treatment in all BC subtypes increased recently." (PMID 37902839, 2024). "AR plays a crucial role in prostate cancer and is also important in the development of CRPC." (PMID 38698344, 2024). "Furthermore, a preprint publication has proposed that ONECUT2 facilitates the development of AR-independent prostate cancer by suppressing AR signaling and facilitating NR3C1 transcription." (PMID 39027480, 2024). "AR signaling has previously been identified as an important contributor to prostate cancer development, and AR blockade therapies have been widely used as an essential component of prostate cancer-targeted therapies." (PMID 38254871, 2024). "In addition, PARP7 was reported to MARylate androgen receptor (AR) on its multiple cysteine residues to restrain AR-signaling in prostate cancer cells." (PMID 38734665, 2024). "However, in different types of prostate cancer, such as hormone-sensitive prostate cancer and CRPC, there are qualitative differences in their expression abnormalities and the appearance of AR-v7 variant shear bodies." (PMID 38798700, 2024).
prostate carcinoma (continued). "Also, coadministration of 2.5 μM of EGCG, genistein, and quercetin suppressed the cell proliferation of a prostate cancer cell line (CWR22Rv1) by controlling androgen receptor and NAD (P)H: quinone oxidoreductase 1 (NQO1) expression." (PMID 38474512, 2024). "Prostate cancer (PCa) is primarily driven by aberrant Androgen Receptor (AR) signaling." (PMID 38030789, 2024). "In preclinical prostate cancer models, supraphysiologic testosterone inhibited cell cycle progression, induced double-strand DNA breaks and genomic rearrangements, and downregulated AR as well as constitutively active AR splice variants." (PMID 38167882, 2024). "In 4 prostate cancer cell lines, which collectively model castration-sensitive disease (LNCaP), AR-positive CRPC (V16D), AR-positive enzalutamide-resistant CRPC (MR49F) and AR-negative CRPC (PC3), we observed a significant additive anti-proliferative effect when combing CDKI-73 and AZD5153." (PMID 39117800, 2024). "Consequently, androgen deprivation therapy (ADT), which diminishes circulating testosterone levels and blocks cellular AR signaling via surgical or chemical castration, remains the cornerstone of treatment for prostate cancer." (PMID 38702734, 2024). "However, despite the initial positive response, prolonged androgen receptor suppression often leads to prostate cancer resistance, progressing to the castration-resistant prostate cancer stage, also known as androgen-independent prostate cancer." (PMID 38921890, 2024). "Other AR-positive prostate cancer cell lines generally display decreases in HLA expression when compared with immortalized benign controls, and cells that maintain AR expression after enza-resistance show increased HLA expression, as evidenced by previous reports." (PMID 38820127, 2024). "Therefore, as a clinically proven mainstream target, AR function inhibition has become an important strategy for prostate cancer treatment." (PMID 39535155, 2024). "Furthermore, CTS interferes with the interaction between AR and the histone demethylase LSD1, preventing the demethylation of histone H3 at lysine 9 (H3-K9), thus inhibiting AR-mediated gene activation and prostate cancer growth." (PMID 39199550, 2024). "It has been speculated that the role of IGF2BP2/3 in regulating the stability of target genes in prostate cancer may be affected by the expression level of AR, but the precise mechanism remains unclear." (PMID 38384328, 2024). "This has, for instance, been reported for the AR in prostate cancer." (PMID 38255778, 2024). "Additionally, bavdegalutamide has demonstrated superior inhibition of tumor growth compared with enzalutamide in various AR-positive prostate cancer xenograft models in mice, solidifying its effectiveness." (PMID 38675453, 2024). "The androgen receptor (AR) is a drug target used to inhibit AR and prostate cancer (PCa) growth." (PMID 38902772, 2024). "The androgen receptor (AR), a member of the nuclear steroid hormone receptor family of transcription factors, plays a crucial role not only in the development of the male phenotype but also in the development and growth of prostate cancer." (PMID 39451211, 2024). "It negatively regulates tank binding kinase 1 activity, which restrains phosphorylation and activation of the transcription factor IRF3, inhibiting androgen‐induced ADP‐ribosylation of the androgen receptor in prostate cancer and trapping PARP7 within the nucleus." (PMID 38342608, 2024). "Furthermore, Pin1 can interact with the N-terminal domain region of the androgen receptor in prostate cancer." (PMID 39624096, 2024). "The first observed crosstalk partner of GR in prostate cancer was AR." (PMID 39027480, 2024). "AR dysregulation is a driver of many human diseases including prostate cancer." (PMID 38554103, 2024).
prostate carcinoma (continued). "Bicalutamide, a nonsteroidal androgen receptor inhibitor, is an established therapeutic agent for advanced prostate cancer but is associated with severe cardiovascular side effects in rare cases." (PMID 38872672, 2024). "This study retrospectively evaluated the clinical outcomes of second-line treatment with docetaxel or androgen receptor signaling inhibitor in patients with castration-resistant prostate cancer who received first-line treatment with androgen receptor signaling inhibitors." (PMID 39135744, 2024). "For prostate cancer patients, the expression of AR-Vs alters the treatments that are recommended." (PMID 38339092, 2024). "Besides prostate cancer and BC, AR signaling seems to contribute to tumor growth in several other malignancies that are not classically hormone-dependent, such as lung, renal, bladder, gastric, hepatocellular, or pancreatic cancer." (PMID 39768587, 2024). "Initially, prostate cancer relies on the androgen receptor (AR) to elicit survival and metastasis." (PMID 39000112, 2024). "Interestingly, AR c.2180G>T (R727L) was detected in unrelated and familial Finnish prostate cancer patients." (PMID 38773237, 2024). "For this reason, AR therapy is an essential tool in the fight against prostate cancer." (PMID 39114070, 2024). "The androgen receptor-related pathway has been identified as a pivotal role in prostate cancer." (PMID 38341429, 2024). "Another study indicated that two naturally occurring sesquiterpenoids (ST1 and ST2) could inhibit the expression of SRC-1 and AR in prostate cancer cells and suppress the nuclear transport of AR, further inhibiting the interaction between SRC-1 and AR." (PMID 38553750, 2024). "To validate this, we conducted western blot analyses in VCaP cells treated with 1 μm UBX‐390 for 4, 24, or 72 h and found a decrease in the levels of proteins related to the AR pathway and prostate cancer biology (i.e., Myc and NK3 homeobox 1 (NKX3.1)) over time following treatment." (PMID 38958553, 2024). "A ChIP-seq of (acK13)-HOXB13, HOXB13, and H3K27ac signals analysis in tumour and normal samples has revealed that (acK13)-HOXB13 occupies an SE targeting lineage (AR, HOXB13), CRPC promoting (ACK1), prostate cancer diagnostic (FOLH1, SPON2), and angiogenesis-related (VEGFA) genes in cancer samples." (PMID 38542080, 2024). "In advanced prostate cancer, up to 15%–20% of patients develop resistance to androgen receptor–directed (AR-directed) therapies through conversion from an androgen-driven adenocarcinoma to an alternative lineage state such as neuroendocrine prostate cancer (NEPC)." (PMID 39024561, 2024). "Another important consideration is that we used publicly available prostate cancer data to inform us of transcripts that may be regulated by the AR in the placenta, as determined by the presence of an ARE full site." (PMID 38338965, 2024). "AHR is involved in various cellular processes relevant to cancer, including cell cycle regulation, modulation of the immune response, and interaction with hormone receptor signaling pathways, particularly the Androgen Receptor (AR) signaling pathway, which is central to prostate cancer progression." (PMID 39600743, 2024). "AR mRNA transcription is downregulated after androgen exposure in prostate, testis, epididymis, seminal vesicle, kidney genital skin fibroblasts, brain and the human prostate cancer cell line, LNCaP." (PMID 39337689, 2024). "Due to mutations in their AR, these cells can be continuously activated and maintain the physiological functions of prostate cancer cells even in the absence of androgen." (PMID 38731782, 2024). "Crosstalk between these pathways and AR enhances prostate cancer tumor growth." (PMID 39000269, 2024). "In addition, TRIM33 significantly enhances AR transcriptional activity by preventing Skp2-mediated degradation of AR, thereby promoting prostate cancer growth." (PMID 39160596, 2024).